AIM2 (absent in melanoma 2)
Diseases named in the same sentence as AIM2 in open-access papers (continued):
Sharing a sentence is not in itself a finding about the gene and the disease.
fatty liver disease (4 papers, 2015 to 2025). A reversible condition wherein large vacuoles of triglyceride fat accumulate in liver cells via the process of steatosis. "For example, oxidative stress occurring in hepatic steatosis leads to mitochondrial damage, release of mtDNA, and subsequent activation of the AIM2 inflammasome." (PMID 39076969, 2024). "AIM2 plays a significant role in the progression of fatty liver disease, including NAFLD and NASH." (PMID 39158380, 2025). "Overexpression of farnesoid X receptor (FXR), (NSAID)‐activated gene‐1 (NAG‐1), and growth differentiation factor‐15 (GDF15) ameliorates liver steatosis, reduces lipogenesis, and enhances lipolysis and fatty acid β‐oxidation, while concurrently suppressing AIM2 inflammasome activation." (PMID 39158380, 2025). "AIM2 inflammasome released IL-18 and IL-1 β after activation, which promoted hepatic steatosis." (PMID 39600708, 2024). "Our results showed that the expression of AIM2 is positively correlated with IL-1β and IL-18 expression in CHB patients and not correlated in the control fatty liver disease patient group." (PMID 26290184, 2015).
Francisella tularensis infection (4 papers, 2017 to 2025). "For the AIM2 inflammasome, Irf3-deficient mouse macrophages, which are unable to secrete type I interferons, have impaired AIM2 activation in response to Francisella tularensis infection, indicating that an intact, type I interferon response is required for AIM2 activation." (PMID 29120406, 2017). "In Francisella tularensis infections, STING-dependent type I IFN production is necessary for the activation of the AIM2 inflammasome, possibly due to the ability of type I IFNs to activate guanylate-binding proteins (GBPs) by increasing bacteriolysis and the release of DNA into the cytosol." (PMID 37261352, 2023).
lupus nephritis (4 papers, 2022 to 2024). Glomerulonephritis in the context of systemic lupus erythematosus. "Several studies have found that AIM2 inflammasome is closely associated with renal diseases, including lupus nephritis and hepatitis B-associated glomerulonephritis." (PMID 35155498, 2022). "In mice in which AIM2 is conditionally ablated in T cells, the severity of pristane-induced lupus nephritis is reduced relative to control animals." (PMID 37081890, 2023). "Furthermore, pristane-induced lupus nephritis is attenuated in mice in which AIM2 is conditionally ablated in B cells." (PMID 37081890, 2023). "Additionally, it has been reported that AIM2 inflammasome also affects the infiltration of macrophages in the kidney, aggravating the progress of lupus nephritis and UUO-induced renal fibrosis." (PMID 35155498, 2022). "Here, we demonstrate for the first time that the DNA sensors AIM2 and IFI16 bind to NETs in vivo, through imaging studies of proliferative lupus nephritis specimens." (PMID 35608258, 2022).
myocardial infarction (4 papers, 2020 to 2024). Gross necrosis of the myocardium, as a result of interruption of the blood supply to the area, as in coronary thrombosis. "AIM2 inflammasome is hyper-activated in type-2 diabetic mice with myocardial infarction." (PMID 33584697, 2020).
Parkinson disease (4 papers, 2018 to 2024). A progressive degenerative disorder of the central nervous system characterized by loss of dopamine producing neurons in the substantia nigra and the presence of Lewy bodies in the substantia nigra and locus coeruleus. "AIM2 inflammasome activity was augmented by inhibition of Parkinson’s disease-associated mitochondrial serine protease." (PMID 33584697, 2020). "In animal models of experimental autoimmune encephalomyelitis (EAE) and Parkinson’s disease (PD), AIM2 molecules in microglia had been observed to negatively regulate the disease independently of inflammasome activation." (PMID 39600708, 2024). "Here, we report that the Parkinson’s disease-associated mitochondrial serine protease HtrA2 restricts the activation of ASC-dependent NLRP3 and AIM2 inflammasomes, in a protease activity-dependent manner." (PMID 29855523, 2018).
prostate tumors (4 papers, 2016 to 2023). "Our observations support the idea that hypoxia in human prostatic tumors contributes to PCI, in part, by priming cells for the activation of NLRP3 and AIM2 inflammasome." (PMID 27058421, 2016).
pulpitis (4 papers, 2020 to 2025). Inflammation of the dental pulp. "The AIM2 inflammasome activation promoted the development of pulpitis." (PMID 39600708, 2024). "Furthermore, in our studies on the mechanism of pulpitis, we demonstrated that AIM2 and NLRP3 inflammasomes are highly expressed in inflamed pulp tissues." (PMID 37250902, 2023). "The expression of AIM2 in rat or human pulpitis tissue has been reported separately but has a similar distribution pattern: AIM2 was only expressed in the odontoblasts of healthy pulp tissue, whereas AIM2 was robustly expressed in the inflammatory cells and fibroblasts of pulpitis tissue." (PMID 32903550, 2020).
renal fibrosis (4 papers, 2020 to 2024). A final common manifestation of a wide variety of chronic kidney diseases characterized by glomerulosclerosis and tubulointerstitial fibrosis. "Knock-out of Nlrp3 and Aim2 resulted in less injury, inflammation, and renal fibrosis after obstruction." (PMID 33117389, 2020). "Komada and colleagues found that renal resident macrophages that take up dsDNA from necrotic cells activate the AIM2 inflammasome signaling pathway, ultimately exacerbating UUO-induced renal fibrosis and inflammation; in contrast, the knockout of the AIM2 gene effectively reduces these effects." (PMID 35155498, 2022). "Knocking down Aim2 and NLRP3 can alleviate renal fibrosis, inflammation, and injury." (PMID 34017258, 2021).
acute myeloid leukemia (3 papers, 2022 to 2025). Acute myeloid leukemia (AML) is a group of neoplasms arising from precursor cells committed to the myeloid cell-line differentiation. "Conversely, in acute myeloid leukemia (AML) cell lines, curcumin has been found to activate the NLRC4, AIM2, and IFI16 inflammasomes, inducing pyroptosis through the upregulation of the ISG3 transcription factor." (PMID 40725015, 2025). "In models of acute myeloid leukemia (AML), curcumin appears to operate through a non-canonical inflammasome pathway by upregulating interferon-stimulated gene ISG3, thereby activating NLRC4, AIM2, and IFI16 inflammasome sensors." (PMID 40806716, 2025).
acute respiratory distress syndrome (3 papers, 2022 to 2025). Progressive and life-threatening pulmonary distress in the absence of an underlying pulmonary condition, usually following major trauma or surgery. "A contribution for AIM2 in NETS detection was reported in a lipopolysaccharide (LPS)-induced acute respiratory distress syndrome (ARDS) model during which intracellular NET-DNA binds the AIM2 receptor to activate the inflammasome ultimately resulting in alveolar macrophage pyroptosis." (PMID 37187738, 2023). "Release of mtDNA and activation of the AIM2/NLRP3 inflammasome have been suggested to play a role in acute respiratory distress syndrome (ARDS) and acute lung injury (ALI)." (PMID 40264103, 2025).
aneurysm (3 papers, 2020 to 2025). Bulging or ballooning in an area of an artery secondary to arterial wall weakening. "In contrast, in Aim2-deficient mice, all aneurysms were located in the infrarenal aorta." (PMID 32933486, 2020).
aspergillosis (3 papers, 2015 to 2022). Aspergillosis is an infection, growth, or allergic response caused by the Aspergillus fungus. "In addition, AIM2 and NLRP3 activity in both the hematopoietic and the stromal compartments is required to protect the host against aspergillosis." (PMID 26204108, 2015). "Mice lacking both AIM2 and NLRP3 were highly susceptible to aspergillosis, indicating that AIM2 might be co-activated with NLRP3." (PMID 35639503, 2022). "In an invasive pulmonary model of aspergillosis, NLRP3 and AIM2 were required to engage the inflammasome to trigger innate immune responses against A. fumigatus; mice lacking both AIM2 and NLRP3, but not mice lacking a single inflammasome receptor, were hyper susceptible to invasive aspergillosis." (PMID 28740491, 2017).
brain injury (3 papers, 2022 to 2024). Acute and chronic (see also brain INJURIES, CHRONIC) injuries to the brain, including the cerebral hemispheres, CEREBELLUM, and brain STEM. "Brain injury results in an increase in dsDNA in the blood, causing AIM2 inflammasome activation in blood monocytes and IL-1β release, which subsequently induces FAS ligand (FASL)-FAS-dependent T cell apoptosis leading to immunosuppression." (PMID 37216118, 2023). "In addition to traumatic brain injury and central nervous system infections, AIM2 inflammasomes have been reported to be associated with ischemic brain injury." (PMID 39636891, 2024).
brucellosis (3 papers, 2020 to 2024). Brucellosis is a bacterial infection that spreads from animals to people via unpasteurized dairy products or by exposure to contaminated animal products or infected animals. "A recent study investigated the role of AIM2 during brucellosis, a zoonotic infection that is often associated with liver fibrosis." (PMID 32906750, 2020). "Acute brucellosis patients exhibit higher AIM2 and lower ASC expression, while chronic brucellosis patients show the opposite pattern." (PMID 39100670, 2024). "Su X and colleagues extended this research by examining AIM2 inflammasome expression in Chinese patients with acute and chronic brucellosis." (PMID 39100670, 2024). "In this study, AIM2 expression is significantly higher in patients with acute brucellosis but lower in chronic brucellosis patients than in healthy controls." (PMID 36068262, 2022). "The expression of AIM2 is higher in acute brucellosis patients but lower in chronic brucellosis than in healthy controls." (PMID 36068262, 2022). "In the acute brucellosis group, AIM2 expression was significantly higher, while ACS expression was significantly lower than that of healthy volunteers." (PMID 36068262, 2022). "In patients with chronic brucellosis, AIM2 expression was significantly lower, while Caspase-1 expression was significantly higher than that of healthy volunteers." (PMID 36068262, 2022). "The results suggest that AIM2 may play a vital role in activating adaptive immune responses in brucellosis patients." (PMID 36068262, 2022). "Collectively, these results suggest that AIM2 promotes liver fibrosis during brucellosis." (PMID 32906750, 2020). "Moreover, we found differences in AIM2 between acute and chronic brucellosis." (PMID 36068262, 2022). "This study aims to investigate the expression levels of AIM2, NLRP3, ASC, and Caspase-1 inflammasomes in acute and chronic brucellosis patients to reveal the possible mechanism of Brucella immune escape." (PMID 36068262, 2022). "The expression levels of AIM2, NLRP3, ASC, and Caspase-1 were investigated in patients with acute brucellosis and chronic brucellosis as well as healthy controls." (PMID 36068262, 2022). "Compared with healthy controls, chronic brucellosis patients present an increasing tendency of NLRP3, significantly decreased AIM2 expression, and significantly increased Caspase-1 expression, with no significant changes in ASC." (PMID 36068262, 2022). "However, AIM2 inflammasome changes in patients with brucellosis at different stages remain unknown." (PMID 36068262, 2022). "Compared with healthy controls, patients with acute brucellosis show significantly higher AIM2 expression and significantly lower ACS expression, with no significant changes in NLRP3 but an increasing tendency of Caspase-1 genes." (PMID 36068262, 2022). "Additionally, AIM2 positively correlates with IL-18 expression in acute brucellosis patients and IFN-γ expression in chronic brucellosis patients." (PMID 36068262, 2022).
cardiac hypertrophy (3 papers, 2021 to 2024). "Activation of the AIM2 inflammasome led to cardiac hypertrophy and remodeling." (PMID 39600708, 2024). "AIM2 is increased in the heart from STZ rats, and AIM2 knockdown attenuates cardiac hypertrophy accompanied by improvements in the diastolic and systolic function." (PMID 35004869, 2021).
chronic hepatitis (3 papers, 2023 to 2025). An active inflammatory process affecting the liver for more than six months. "In HBV infection, the expression of AIM2 in peripheral blood monocytes differs in acute versus chronic hepatitis, while in the context of chronic HBV, higher levels of AIM2 correlate with increased inflammation (22, –, 24), but the mechanism is unclear." (PMID 37787533, 2023).
chronic hepatitis B (3 papers, 2013 to 2025). "In this study, the expression AIM2, and its downstream cytokines, caspase-1, IL-18 and IL-1β, in liver tissue of patients with chronic hepatitis B and C (CHB, CHC) were investigated." (PMID 26290184, 2015). "A recent study focusing on the relationship between AIM2 expression and acute and chronic hepatitis B infection showed that AIM2 mRNA expression was negatively correlated with serum HBV load." (PMID 24325587, 2013). "The present study showed the expression of AIM2 is correlated with increased inflammation in patients with chronic hepatitis B. AIM2 upregulation may be a component of HBV immunopathology." (PMID 26290184, 2015).
diabetic cardiomyopathy (3 papers, 2022 to 2025). Diabetic cardiomyopathy is a disorder of the heart muscle in people with diabetes. "In diabetic cardiomyopathy, AIM2 promotes reactive oxygen species (ROS) production and induces cardiomyocyte apoptosis." (PMID 41462520, 2025). "In addition, some studies have shown that AIM2 plays an important role in myocardial cell death and fibrosis through the GSDMD pathway in high glucose-induced ROS-mediated diabetic cardiomyopathy, and inhibition of AIM2 expression reduces progression of diabetic cardiomyopathy (DCM)." (PMID 36993972, 2023).
endothelial dysfunction (3 papers, 2021 to 2025). In vascular diseases, endothelial dysfunction is a systemic pathological state of the endothelium (the inner lining of blood vessels) and can be broadly defined as an imbalance between vasodilating and vasoconstricting substances produced by (or acting on) the endothelium. "Finally, it must be stressed that inflammasomes other than NLRP3, such as AIM2, NLRP1, NLRC4, and NLRP6, have not been thoroughly investigated so far in the context of the development of endothelial dysfunction and the impact on pathogenesis and progression of T2DM." (PMID 33546399, 2021).
fibrosis (3 papers, 2020 to 2022). the formation of excess fibrous connective tissue in an organ or tissue in a reparative or reactive process. "We found that the stimulation of AIM2 led to IL-1α, IFN-α and TGF-β release from fibrosis-associated circulating cells from PC patients." (PMID 35844548, 2022). "Together, these studies touch on the possible role of AIM2 during HSC activation, fibrogenesis, and the inflammatory complications of advanced fibrosis and cirrhosis." (PMID 32906750, 2020).
fungal infections (3 papers, 2017 to 2025). "In summary, the AIM2 inflammasome has a double effect in fungal infections, causing either protection or disease." (PMID 41459537, 2025). "However, based on our current study, the overexpression of Aim2 may increase the risk of fungal infection in patients." (PMID 38918243, 2024). "Research on AIM2 in fungal infections highlights its collaborative role with NLRP3 in inducing the assembly of inflammasomes during Aspergillus fumigatus infection." (PMID 41459537, 2025). "During the course of a fungal infection, the activation of inflammasomes such as AIM2 has been observed to promote caspase-1-mediated pyroptosis, resulting in the demise of infected cells and the direct elimination of sites of fungal replication." (PMID 41459537, 2025). "In order to investigate the possible involvement of AIM2 in host defense against systemic fungal infection, WT and Aim2−/− mice were chosen for systemic C. albicans infection." (PMID 38918243, 2024). "The clinical researches can be conducted to explore the potential of manipulating AIM2 to control fungal infection in the future." (PMID 38918243, 2024). "With respect to inflammasome activation upon fungal infections, only the inflammasome receptors AIM2, NLRC4 and, mainly, NLRP3, are related to engaging and triggering IL-1β caspase-dependent cleavage." (PMID 29209318, 2017). "The targeting of AIM2 or AKT may hold therapeutic implications for the treatment of systemic fungal infections." (PMID 38918243, 2024). "We provide a mechanistic analysis of AIM2-Akt-apoptosis axis in enhancing fungal infection." (PMID 38918243, 2024). "The research on the role of AIM2 in fungal infection is still limited to the experimental studies." (PMID 38918243, 2024). "Furthermore, our investigation also indicates that some small molecule such as AIM2 inhibitors can be applied to suppress invasive fungal infection." (PMID 38918243, 2024). "Currently, there is a paucity of research on the role of AIM2 in fungal infections." (PMID 38918243, 2024). "This suggests that AIM2 and AKT may represent promising therapeutic targets for the management of fungal infections." (PMID 38918243, 2024).
lung adenocarcinoma (3 papers, 2021 to 2025). A carcinoma that arises from the lung and is characterized by the presence of malignant glandular epithelial cells. "We further analyzed the influence of core genes on lung adenocarcinoma prognosis, and survival analysis revealed a significant association between CASP1, NLRP3, NLRP1, and AIM2 and overall survival in patients with lung adenocarcinoma." (PMID 40026444, 2025). "Our focus was constructing a diagnostic and prognostic model for lung adenocarcinoma based on the core genes—CASP1, NLRP3, AIM2, and NLRP1." (PMID 40026444, 2025). "CASP1, NLRP3, AIM2, and NLRP1 are core pyroptotic genes in lung adenocarcinoma, significantly associated with immune cell infiltration, diagnosis, and prognosis in this condition." (PMID 40026444, 2025). "The results showed that CASP1, NLRP3, AIM2, and NLRP1 exhibited excellent diagnostic efficacy, suggesting their potential utility as diagnostic biomarkers for lung adenocarcinoma." (PMID 40026444, 2025). "Our findings indicate that CDKN1A inhibits the activation of AIM2 inflammasome by promoting DNA repair after radiotherapy, thus promoting the survival of lung adenocarcinoma cells." (PMID 38468925, 2024). "Evaluation using ROC curves for core genes indicated that CASP1, NLRP3, AIM2, and NLRP1 demonstrate excellent diagnostic potential for lung adenocarcinoma and may serve as diagnostic markers for the disease." (PMID 40026444, 2025). "This further confirms the pyroptosis core gene CASP1, NLRP3, AIM2, and NLRP1 expression levels in lung adenocarcinoma and their connection to immune infiltration." (PMID 40026444, 2025). "We found that the AIM2 inflammasome is at the crosstalk between smoking-induced COPD and lung adenocarcinoma." (PMID 34084280, 2021). "However, to understand the role of AIM2 as an upstream inflammasome receptor, we analyzed the expression of AIM2 in lung tumor vs non-cancerous tissues obtained from lung adenocarcinoma patients undergoing surgical resection (n = 36)." (PMID 34084280, 2021).
Oral Cancer (3 papers, 2021 to 2025). "All together, these pieces of evidence suggest the pro-carcinogenic role of AIM2 in oral cancers." (PMID 40002808, 2025). "Thus, according to the role of the innate immune system in providing non-specific protection and enhancing the adaptive immune response against a variety of pathogens, including HPV, a role for the cytosolic dsDNA sensor AIM2 in oral cancer was suggested." (PMID 40002808, 2025). "Besides, AIM2 and GSDMD showed higher expression in oral cancer cells than HOK cells, especially in HSC-4 cells." (PMID 34384029, 2021).